GTSE1 (G2 and S-phase expressed 1)
Description:
Overexpression delays G2/M phase progression.
Synonyms: GTSE-1; B99; Lnc_bc060912
Tractability: Antibody: the Human Protein Atlas places it where antibodies can reach. PROTAC: ubiquitination databases record sites on it.
Gene: Protein-coding gene on chromosome 22 (46,296,870 to 46,330,810, forward strand). Ensembl gene ENSG00000075218.
Subcellular location: Cytoplasm, cytoskeleton
Subcellular location (Human Protein Atlas): Centrosome; Plasma membrane; Basal body; Cytosol; Nucleoplasm; Primary cilium; Primary cilium tip
Pathways (Reactome):
Cell Cycle: G2/M Checkpoints; The role of GTSE1 in G2/M progression after G2 checkpoint
Gene Ontology:
Molecular function: protein binding; microtubule binding
Biological process: microtubule-based process
Cellular component: cytoplasmic microtubule; membrane; plasma membrane; cytosol; microtubule cytoskeleton; nucleoplasm; cytoskeleton
Genetic constraint (gnomAD): Loss-of-function variants: 39 observed, 49.66 expected, observed/expected ratio (o/e) 0.79, 90% interval 0.61 to 1.03. The upper end of that interval is the gene's LOEUF score, 1.03, which puts it in group 4 of 6, group 1 being the genes least tolerant of losing a copy. Missense variants: 823 observed, 868.68 expected, observed/expected ratio (o/e) 0.95, 90% interval 0.89 to 1. Synonymous variants: 324 observed, 350.86 expected, observed/expected ratio (o/e) 0.92, 90% interval 0.84 to 1.01.
Homologues: Orthologues: chimpanzee GTSE1 (98% identical), macaque GTSE1 (88% identical), rabbit GTSE1 (63% identical), dog GTSE1 (62% identical), rat Gtse1 (56% identical), mouse Gtse1 (56% identical), guinea pig GTSE1 (52% identical), pig GTSE1 (52% identical), tropical clawed frog gtse1 (32% identical), zebrafish gtse1 (27% identical). Paralogues in human: PSRC1 (11% identical).
Diseases named in the same sentence as GTSE1 in open-access papers:
GTSE1 is named in the same sentence as 60 diseases in open-access papers, as found by Europe PMC text mining. Sharing a sentence is not in itself a finding about the gene and the disease. The quoted sentences say what the papers report.
breast carcinoma (18 papers, 2012 to 2024). "In the present study, we showed that GTSE1 was associated with worse outcome and malignant phenotype including enhanced abilities of tumor proliferation and metastasis in breast cancer." (PMID 30961661, 2019). "We previously investigated the relationship between breast cancer clinical variables and GTSE1 expression noticing its association with the most invasive and aggressive cancers (Grade 3)." (PMID 28978043, 2017). "These genes are implicated in microtubule dynamics and, among them, GTSE1 has emerged as a microtubule-associated protein that is correlated with tumour metastasis in breast cancer." (PMID 23945276, 2013). "We next looked for a causal link between GTSE1 expression and migratory ability in two breast cancer cell lines." (PMID 23236459, 2012). "Up-regulation of GTSE1 expression could be associated with increased invasive potential in breast cancer." (PMID 30564062, 2018). "In breast cancers, increased GTSE1 expression correlates with invasive potential, tumor stage, and time to distant metastasis, suggesting that misregulation of GTSE1 expression could be associated with increased invasive potential." (PMID 23236459, 2012). "Moreover, GTSE1 can cause multidrug resistance in breast cancer cells." (PMID 32180800, 2020). "The role of GTSE1 in drug resistance is shown in gastric cancer cells, osteosarcoma, breast cancer, clear cell renal cell carcinoma, and non-small-cell lung cancer." (PMID 38698443, 2024). "Increased expression of GTSE1 was found in several human malignancies, such as lung cancer, breast carcinoma, and hepatocellular carcinoma and was correlated with unfavorable prognosis." (PMID 34876170, 2021). "The GTSE1 gene promotes cell growth in breast cancer by activating the P13-Akt pathway and enhances metastasis." (PMID 34070979, 2021). "GTSE1 mRNA expression level and the GTSE1 protein level was higher in the breast cancer tissues as compared to the normal breast tissues." (PMID 30961661, 2019). "The expression level of GTSE1 protein in breast cancer tissues was related to differentiation and reduced overall survival time and recurrence free survival time of patients." (PMID 30961661, 2019). "The biological function of GTSE1 in the growth, migration and invasion of breast cancer was examined in MDA-MB-231, MDA-MB-468 and MCF7 cell lines." (PMID 30961661, 2019). "To investigate the role of GTSE1 in breast cancer cell proliferation, we transfected MDA-MB-231 and MDA-MB-468 cells with siRNA (GTSE1 si#1) and negative control siRNA." (PMID 30961661, 2019). "Taken together, we brought light on the function of GTSE1 and showed its potential significance as a novel biomarker for assessing the breast cancer progression." (PMID 30961661, 2019). "The role of GTSE1 in the growth and metastasis of breast cancer were revealed by in vivo investigation using BALB/c nude mice." (PMID 30961661, 2019). "Immunohistochemistry staining showed that GTSE1 was mainly located in the cytoplasm of breast cancer cells, and its protein expression level was higher in TNBC, which was consistent with the result of the bc-GenExMiner database showing the GTSE1 mRNA level." (PMID 30961661, 2019). "Since the AKT pathway has a crucial influence on breast cancer malignant phenotype, we determined that GTSE1 had an effect on AKT activation." (PMID 30961661, 2019). "GTSE1 over-expression has been reported as a potential marker for metastasis in various types of malignancies, including breast cancer." (PMID 28978043, 2017).
breast carcinoma (continued). "The obtained results suggest that TEAD controls the formation of cell protrusions through GTSE1, providing, for the first time, a mechanical explanation of how it regulates breast cancer cell migration." (PMID 28978043, 2017). "In fact, patients with breast cancer and higher GTSE1 levels show shorter time to distant metastasis and shorter survival time." (PMID 28978043, 2017). "In a previous study, we reported that GTSE1 (G2 and S phase expressed 1) expression was up-regulated in breast cancer, especially in TNBC." (PMID 28978043, 2017). "Since cell protrusions represent a common feature of moving cells in tumors, we wondered if GTSE1 controlled breast cancer cells migration through the regulation of cell protrusions formation." (PMID 28978043, 2017). "Kaplan-Meier survival analysis of the combined data sets showed that breast cancer patients expressing higher GTSE1 levels in tumors displayed both shorter survival time (p<10−9) and a shorter time to distant metastasis (p<10−15)." (PMID 23236459, 2012). "We also found a significant correlation between GTSE1 expression and the grade of breast cancers, with the most invasive and aggressive cancers (Grade 3) showing highest expression of GTSE1." (PMID 23236459, 2012). "To delve deeper into clinical correlations with GTSE1 expression, we analyzed several microarray data sets of breast cancer, collectively consisting of more than 2000 patients." (PMID 23236459, 2012). "To investigate the significance of GTSE1 expression levels in the context of breast cancer cell lines, we next analyzed a panel of lines of varying breast cancer tumor types with different degrees of invasive potential for both GTSE1 and EB1 protein levels." (PMID 23236459, 2012). "GTSE1 was upregulated in breast cancer, lung cancer, and colon cancer." (PMID 37723560, 2023). "Furthermore, our results also showed that GTSE1 knockdown inhibited cell proliferation and clone formation in A549 and H460 cells, which is in accord with the data on hepatocellular carcinoma and breast cancer." (PMID 34007784, 2021). "High expression of GTSE1 can promote breast cancer growth and metastasis." (PMID 32180800, 2020). "Taken together, our study demonstrated that GTSE1 could serve as a novel and potential marker for the prognosis of breast cancer." (PMID 30961661, 2019). "Our functional studies demonstrated that GTSE1 could promote the growth of breast cancer cells, which is in line with the data on HCC." (PMID 30961661, 2019). "Previous studies have also reported that GTSE1 was identified as a novel YAP/TAZ-TEAD4 regulatory protein that could promote metastasis in breast cancer cells when it is overexpressed, especially in TNBC." (PMID 30961661, 2019). "We demonstrated that GTSE1 could promote breast cancer cell growth by activating the AKT pathway and enhance metastasis by regulating the Epithelial-Mesenchymal transition (EMT) pathway." (PMID 30961661, 2019). "These suggest that GTSE1 could promote breast cancer growth at least partially by activating the AKT pathway." (PMID 30961661, 2019). "Therefore, the role of GTSE1 should be explored further as a candidate marker for the prognosis of breast cancer, and signaling pathway research will enhance our understanding of its function in the progression of breast cancer." (PMID 30961661, 2019). "Our results reveal that GTSE1 played a key role in the progression of breast cancer, indicating that GTSE1 could serve as a novel biomarker to aid in the assessment of the prognosis of breast cancer." (PMID 30961661, 2019). "In summary, GTSE1 have effects on regulation of breast cancer growth and metastasis." (PMID 30961661, 2019). "For these reasons, we verified if TEAD controlled breast cancer cells migration through GTSE1." (PMID 28978043, 2017).
breast carcinoma (continued). "Interestingly, GTSE1 up-regulation was identified as a potential marker for metastasis not only in breast cancer but also in gastroenteropancreatic neuroendocrine tumor, oral tongue squamous cell carcinoma and hepatocellular carcinoma." (PMID 28978043, 2017). "As mentioned, GTSE1 activity is another feature required for breast cancer cells migration." (PMID 28978043, 2017). "The increased GTSE1 correlates with the invasive potential of breast cancers." (PMID 25648588, 2014). "Notably, clinical outcome correlated with increased GTSE1 expression in 12 cases, 10 of which were in breast cancer." (PMID 23236459, 2012). "Thus GTSE1 protein levels correlate with invasiveness and metastasis in clinical breast cancer tumors, and determine cell migratory capacity in breast cancer cell lines." (PMID 23236459, 2012). "Hence, we demonstrated that GTSE1 could promote breast cancer cells invasion and metastasis by regulating the epithelial-mesenchymal transition." (PMID 30961661, 2019). "Moreover, flow cytometry was used to determine whether the role of GTSE1 in breast cancer cell proliferation affected cell cycle progression." (PMID 30961661, 2019). "In addition, our data demonstrated that GTSE1 may affect the AKT pathway to facilitate breast cancer cells growth." (PMID 30961661, 2019). "Moreover, our data also indicated that GTSE1 could enhance breast cancer cells metastasis by regulating EMT, which is in line with the data on HCC." (PMID 30961661, 2019). "Moreover, GTSE1 contributed to multidrug resistance in breast cancer cells." (PMID 30961661, 2019). "This is even more relevant to be considered since GTSE1 is also expressed at high levels in subtypes other than TNBC, such as HER2+ and luminal B breast cancers, as we have shown, and in other tumor types." (PMID 28978043, 2017). "In breast cancer, the protein levels of GTSE1 were shown to determine the migratory capacity of nontransformed breast cancer cell lines." (PMID 34007784, 2021). "Ectopic expression of GTSE1 increased the phosphorylated AKT levels without affecting the total AKT levels in breast cancer cells." (PMID 30961661, 2019). "We had previously reported that GTSE1 is required for TNBC cell migration and another study had also demonstrated that YAP, TAZ and TEAD down-regulation impacts negatively on the ability of breast cancer cells to migrate." (PMID 28978043, 2017). "Similarly to GTSE1, HMMR is regulated by both TEAD4 and E2F1 and has a critical role in breast cancer cell migration." (PMID 28978043, 2017). "Here, we report that the palbociclib treatment leads to a reduction of the expression of both GTSE1 and HMMR, suggesting that they may contribute to the reduced breast cancer cell migration." (PMID 28978043, 2017). "Furthermore, our current data also showed that GTSE1 knockdown inhibited proliferation, migration, and invasion and induced apoptosis of HCC cells in vitro, which is consistent with the data on breast cancer." (PMID 27240802, 2016). "GTSE1 protein levels determine the migratory capacity of both nontransformed and breast cancer cell lines." (PMID 23236459, 2012). "However, up to now, there has been no detailed study regarding the functional role of GTSE1 in breast cancer." (PMID 30961661, 2019). "Since GTSE1 could promote the proliferative ability of breast cancer cells, we found that it had no function on breast cancer cells spontaneous apoptosis but affected the cell cycle distribution." (PMID 30961661, 2019).
breast carcinoma (continued). "However, since GTSE1 affects breast cancer differentiation without affecting self-renewal ability, we assumed that GTSE1 may regulate the differentiation of breast cancer cells by influencing other biological processes such as EMT and cell cycle." (PMID 30961661, 2019). "Moreover, we found that TEAD4 controls the formation of cell protrusions required for cell migration through GTSE1, unveiling a relevant effector role for this protein in the TEAD-dependent cellular functions and confirming TEAD4 role in promoting invasion and metastasis in breast cancer." (PMID 28978043, 2017).
lung carcinoma (12 papers, 2015 to 2024). "The up-regulation of GTSE1 in lung cancer patients is associated with disease progression and a reduced survival rate." (PMID 39275122, 2024). "Previous studies have shown that GTSE1 is upregulated in lung cancer (LC) and is considered a potential risk gene for LC development." (PMID 39629227, 2024). "For instance, GTSE1, as a cell cycle-associated protein, exerts a proliferative role in multiple tumors, such as prostate cancer, lung cancer, and bladder cancer." (PMID 36999057, 2023). "It has been shown that amplification of GTSE1 gene has been found in lung cancer, and high GTSE1 expression was associated with the histological types." (PMID 27240802, 2016). "In conclusion, we defined high GTSE1 expression as a worse prognostic trigger for lung cancer patients and reported that GTSE1 acts as an oncogene by activating AKT/mTOR signaling in the lung cancer." (PMID 34007784, 2021). "In this study, we demonstrated that GTSE1 was upregulated and correlated with worse outcome in lung cancer." (PMID 34007784, 2021). "Ectopic expression of GTSE1 promoted whereas knockdown of GTSE1 inhibited the proliferation, migration, and invasion of lung cancer cells A549 and H460." (PMID 34007784, 2021). "In conclusion, these results indicated that the overexpressed GTSE1 was involved in the progress of lung cancer by promoting proliferation migration and invasion and inhibiting apoptosis of lung cancer cells via activating AKT/mTOR signaling." (PMID 34007784, 2021). "Consistent with this study, we reported that cell invasion and migration in lung cancer were dependent on the GTSE1 expression levels." (PMID 34007784, 2021). "By consulting the Oncomine database, we found that the mRNA levels of GTSE1 were higher in lung cancer tissues than in normal lung tissues." (PMID 34007784, 2021). "To investigate the potential molecular mechanism of GTSE1 in regulating lung cancer cells' malignant phenotype, we detected the activation of tumor-related signaling pathways." (PMID 34007784, 2021). "Ectopic expression of GTSE1 in lung cancer cells significantly increased while knockdown of GTSE1 decreased cell proliferation, cell migration, and cell invasion in H460 and A549 cells." (PMID 34007784, 2021). "The Kaplan-Meier plotter analysis database revealed that high GTSE1 expression predicts poorer overall survival of lung cancer patients." (PMID 34007784, 2021). "From TCGA database, we demonstrated that the levels of GTSE1 were increased in lung cancer tissues compared with normal lung tissues." (PMID 34007784, 2021). "GTSE1 has been found to be highly expressed in the tumors such as melanoma and lung cancer and is related to the weak prognosis of the patients." (PMID 32318583, 2020). "After screening 952 CDEGs, we found that the up-regulation of neuromedin U (NMU) and GTSE1 in the case of lung cancer is related to poor prognosis." (PMID 32318583, 2020). "Then, we used lung cancer cells A549, H1299 and H460 for the next experiments, and our data showed that knockdown GTSE1 expression significantly sensitized these cells to IR." (PMID 32202046, 2020). "Previous studies have clearly demonstrated upregulation of GTSE1 expression in lung cancer tissues." (PMID 38715380, 2024). "Previous studies have revealed that GTSE1 could promote the malignant progression of tumors in lung cancer, colon cancer, and liver cancer." (PMID 36999057, 2023). "We will further study the role of GTSE1 in animal models of lung cancer in the future." (PMID 34007784, 2021). "Our results demonstrated that GTSE1 might function as an oncogenic trigger in the development and progression of lung cancer, which may be useful as a therapeutic target for lung cancer." (PMID 34007784, 2021). "In this study, we reported that the expression of GTSE1 was enhanced in lung cancer tissues and cells, and we think that the hypomethylation of the GTSE1 promoter might be responsible for its high expression." (PMID 34007784, 2021).